HMBOX1 (homeobox containing 1)
Description:
Binds directly to 5'-TTAGGG-3' repeats in telomeric DNA. Associates with the telomerase complex at sites of active telomere processing and positively regulates telomere elongation. Important for TERT binding to chromatin, indicating a role in recruitment of the telomerase complex to telomeres (By similarity). Also plays a role in the alternative lengthening of telomeres (ALT) pathway in telomerase-negative cells where it promotes formation and/or maintenance of ALT-associated promyelocytic leukemia bodies (APBs). Enhances formation of telomere C-circles in ALT cells, suggesting a possible role in telomere recombination. Might also be involved in the DNA damage response at telomeres.
Synonyms: HOT1; TAH1; HNF1LA; PBHNF; FLJ21616
Tractability: PROTAC: UniProt records ubiquitination sites on it; ubiquitination databases record sites on it; its protein half-life has been measured.
Gene: Protein-coding gene on chromosome 8 (28,890,292 to 29,064,764, forward strand). Ensembl gene ENSG00000147421.
Subcellular location: Nucleus; Cytoplasm; Chromosome, telomere; Nucleus, Cajal body; Nucleus, PML body; Nucleus (Isoform 5)
Subcellular location (Human Protein Atlas): Nucleoplasm; Cytosol; Nuclear bodies
Gene Ontology:
Molecular function: double-stranded telomeric DNA binding; identical protein binding; protein binding; protein-containing complex binding; sequence-specific DNA binding; sequence-specific double-stranded DNA binding; telomeric DNA binding; DNA binding
Biological process: negative regulation of DNA-templated transcription; negative regulation of transcription by RNA polymerase II; telomere maintenance via telomerase; telomere-telomerase complex assembly; positive regulation of DNA-templated transcription
Cellular component: chromosome, telomeric region; cytoplasm; cytosol; nuclear body; nucleoplasm; nucleus; chromatin; Cajal body; PML body
Genetic constraint (gnomAD): Loss-of-function variants: 8 observed, 34.76 expected, observed/expected ratio (o/e) 0.23, 90% interval 0.13 to 0.41. The upper end of that interval is the gene's LOEUF score, 0.41, which puts it in group 1 of 6, group 1 being the genes least tolerant of losing a copy. Missense variants: 279 observed, 426.97 expected, observed/expected ratio (o/e) 0.65, 90% interval 0.59 to 0.72. Synonymous variants: 138 observed, 156.05 expected, observed/expected ratio (o/e) 0.88, 90% interval 0.77 to 1.02.
Homologues: Orthologues: chimpanzee HMBOX1 (100% identical), macaque HMBOX1 (100% identical), rabbit HMBOX1 (99% identical), pig HMBOX1 (99% identical), mouse Hmbox1 (99% identical), guinea pig HMBOX1 (97% identical), tropical clawed frog hmbox1 (94% identical), dog HMBOX1 (92% identical), rat Hmbox1 (91% identical), zebrafish HMBOX1 (75% identical), zebrafish hmbox1a (74% identical), Caenorhabditis elegans hmbx-1 (25% identical).
Diseases named in the same sentence as HMBOX1 in open-access papers:
HMBOX1 is named in the same sentence as 22 diseases in open-access papers, as found by Europe PMC text mining. Sharing a sentence is not in itself a finding about the gene and the disease. The quoted sentences say what the papers report.
osteosarcoma (16 papers, 2020 to 2025). A usually aggressive malignant bone-forming mesenchymal neoplasm, predominantly affecting adolescents and young adults. "For instance, WTAP, which is highly expressed in osteosarcoma tissues and linked with the worse prognosis of osteosarcoma patients, was found to potentially promote osteosarcoma progression by inhibiting HMBOX1 in an m6A-dependent manner in vitro and in vivo." (PMID 34733885, 2021). "The tumor‐promoting effects of HMBOX1 have been analyzed in various cancers, such as osteosarcoma, cervical cancer, and lung squamous cell carcinoma." (PMID 40008841, 2025). "In osteosarcoma, WTAP inhibits the expression of its potential target gene HMBOX1 through participation in m6A modification, significantly accelerating osteosarcoma development by regulating the PI3K/AKT pathway." (PMID 38649363, 2024). "The HMBOX1 is involved in the proliferation and metastasis of osteosarcoma, which is mediated by WTAP in vitro." (PMID 37915034, 2023). "Another study reported that WTAP can facilitate osteosarcoma oncogenesis by inhibiting the expression of HMBOX1 in an m6A methylation-dependent manner." (PMID 37854284, 2023). "In osteosarcoma, low HMBOX1 expression predicts poor overall survival and is involved in WTAP-mediated proliferation and metastasis of osteosarcoma." (PMID 36139062, 2022). "For example, WTAP suppressed HMBOX1 expression in an m6A-dependent manner in osteosarcoma tumorigenesis." (PMID 33748145, 2021). "Further investigations demonstrated that WTAP/HMBOX1 regulated osteosarcoma growth and metastasis via PI3K/AKT pathway." (PMID 32814762, 2020). "Mechanistically, WTAP induced the growth and metastasis of osteosarcoma via downregulating HMBOX1 expression in m6A-dependent manner." (PMID 32814762, 2020). "We also revealed the lower expression of HMBOX1 in osteosarcoma cell lines (SJSA-1, MG-63, HOS, U2OS, and 143B) than that in the human osteoblast (hFOB1.19) cell line." (PMID 32814762, 2020). "The bioluminescence imaging showed that silenced HMBOX1 alleviated the repression of silenced WTAP on osteosarcoma metastasis." (PMID 32814762, 2020). "Among which, HMBOX1 was the most significantly upregulated gene in shWTAP osteosarcoma cells and was selected for further analysis." (PMID 32814762, 2020). "Consistently, HMBOX1 is downregulated and closely related to the poor prognosis of osteosarcoma in the present study." (PMID 32814762, 2020). "Silenced HMBOX1 evidently attenuated shWTAP-mediated suppression on osteosarcoma growth and metastasis in vivo and vitro." (PMID 32814762, 2020). "The expression levels of HMBOX1 was significantly upregulated by silenced WTAP in subcutaneous osteosarcoma tissue." (PMID 32814762, 2020). "WTAP dramatically promoted osteosarcoma proliferation and metastasis via regulating HMBOX1 mRNA stability in a m6A-dependent manner." (PMID 32814762, 2020). "The similar effects of HMBOX1 were also observed in WTAP-silenced osteosarcoma cell using wound-healing and transwell invasion assays." (PMID 32814762, 2020). "And the survival analysis results showed that the patients with low level HMBOX1 had poor overall survival in osteosarcoma." (PMID 32814762, 2020). "HMBOX1 expression was evidently increased by WTAP knockdown and was decreased by HMBOX1 knockdown in osteosarcoma cells." (PMID 32814762, 2020). "For instance, WTAP, which is highly expressed in osteosarcoma tissues and associated with the worse prognosis of osteosarcoma patients, was found to potentially promote osteosarcoma progression by inhibiting HMBOX1 in an m6A-dependent manner in vitro and in vivo." (PMID 36313417, 2022). "Moreover, WTAP overexpression promotes osteosarcoma tumorigenesis by suppressing homeobox-containing 1 (HMBOX1) expression and is correlated with tumour-associated T lymphocyte infiltration in gastric cancer, indicating a poor prognosis." (PMID 35143566, 2022).
osteosarcoma (continued). "Similarly, WTAP was found to induce the proliferation and metastasis of osteosarcoma by regulating HMBOX1 m6A modification." (PMID 36207306, 2022). "Inhibiting PI3K/AKT pathways can partly reverse WTAP/HMBOX1- induced osteosarcoma progression." (PMID 34094986, 2021). "Moreover, WTAP facilitates the progression of hepatocellular carcinoma via m6A‐HuR‐dependent epigenetic silencing of ETS127 and promotes osteosarcoma tumorigenesis by repressing HMBOX1 expression." (PMID 34595849, 2021). "Moreover, the univariate and multivariate analysis demonstrated HMBOX1 as an independent prognostic factor for overall survival (p = 0.019) in osteosarcoma patients." (PMID 32814762, 2020). "In addition, HMBOX1 expression was downregulated in osteosarcoma and was an independent prognostic factor for overall survival in osteosarcoma patients." (PMID 32814762, 2020). "Moreover, silenced WTAP repressed the tumor size and tumor weight in subcutaneous osteosarcoma mice, which was rescued by silenced HMBOX1." (PMID 32814762, 2020). "Altogether, our results determined WTAP/ HMBOX1 as a potential therapeutic target for osteosarcoma." (PMID 32814762, 2020). "WTAP/HMBOX1 regulated osteosarcoma growth and metastasis via PI3K/AKT pathway." (PMID 32814762, 2020). "We hypothesized that WTAP/HMBOX1 was involved in the progression of osteosarcoma via regulating PI3K/AKT signaling pathway." (PMID 32814762, 2020). "Overall, these results imply that WTAP/HMBOX1 may be an important mechanism of osteosarcoma progression and serve as a novel therapeutically target of osteosarcoma." (PMID 32814762, 2020). "Moreover, we analyzed the relationship between HMBOX1 expression clinicopathological features in 104 osteosarcoma patients from TXHCSU." (PMID 32814762, 2020). "Finally, WTAP/HMBOX1 regulated osteosarcoma growth and metastasis via PI3K/AKT pathway." (PMID 32814762, 2020). "We next explored whether WTAP promoted osteosarcoma progression by regulating HMBOX1 expression." (PMID 32814762, 2020). "Finally, we analyzed the downstream pathway of WTAP/HMBOX1 in osteosarcoma." (PMID 32814762, 2020). "Finally, WTAP/HMBOX1 regulated osteosarcoma growth and metastasis in a PI3K/AKT-dependent pattern." (PMID 32814762, 2020). "WTAP and HMBOX1 modulate the PI3K/AKT pathway to regulate the growth and metastasis of osteosarcoma." (PMID 37915034, 2023). "We next verified the role of HMBOX1 in vivo by injecting shNC, shWTAP, shHMBOX1, and shWTAP/shHMBOX1 U2OS cells to induce subcutaneous osteosarcoma mice model, orthotopic xenograft tumor model, and tail vein metastasis model." (PMID 32814762, 2020). "We next shed light on the expression of YTHDF2 in osteosarcoma and the role of YTHDF2 on HMBOX1 expression in osteosarcoma." (PMID 32814762, 2020). "In conclusion, these results indicated that HMBOX1 is a potential target of WTAP and is related to poor prognosis of osteosarcoma patients." (PMID 32814762, 2020). "Taken together, these results suggest that HMBOX1 is involved in WTAP-mediated tumor growth and metastasis of osteosarcoma." (PMID 32814762, 2020). "In addition, silenced HMBOX1 evidently alleviated WTAP-knockdown-mediated repression of osteosarcoma progression, which implied the import roles of HMBOX1 in WTAP-driven osteosarcoma development." (PMID 32814762, 2020).
ovarian carcinoma (7 papers, 2020 to 2025). A malignant neoplasm originating from the surface ovarian epithelium. "In a study using blood samples from ovarian cancer patients and healthy donors, as well as ovarian cancer cell lines, it was discovered that tRF-03357 inhibits HMBOX1 and promotes SK-OV-3 cell migration, proliferation, and invasion." (PMID 35715825, 2022). "However, the specific pathway involved in tRF-03357 regulating HMBOX1 and other tRFs that modulated the progression of ovarian cancer required further investigation." (PMID 35574338, 2022). "It was reported that tRF-03357 promoted SK-OV-3 cell (an ovarian cancer derived cell line) proliferation, migration and invasion via downregulating its target gene Homeobox-containing protein 1 (HMBOX1) which was a transcription factor belonging to the hepatocyte nuclear factor family." (PMID 36072340, 2022). "HMBOX1 repressed the progression of ovarian cancer via regulating cell proliferation and apoptosis." (PMID 32814762, 2020). "Another group using serum samples from ovarian cancer patients and healthy donors, along with ovarian cancer cell lines, have shown differential expression of tRF; they showed that tRF-03357 promoted SK-OV-3 cell proliferation, migration, and invasion, as well as downregulating HMBOX1." (PMID 33802524, 2021).
gastric cancer (6 papers, 2020 to 2023). A primary or metastatic malignant neoplasm involving the stomach. "For example, high expression of HMBOX1 was observed in gastric cancer, and it was associated with the poor prognosis of gastric cancer." (PMID 32814762, 2020). "It has been found that HMBOX1 is upregulated in gastric cancer and leads to a poor prognosis by promoting cell proliferation and migration." (PMID 33746573, 2021). "Studies revealed that HMBOX1 promotes the proliferation of gastric cancer cells." (PMID 35345489, 2022).
liver cancer (4 papers, 2013 to 2022). An epithelial or non-epithelial malignant neoplasm that arises from the liver. "Meanwhile, the cytotoxicity of NK cells was enhanced through the inhibition of HMBOX1 via specific binding between miR-30c-1 and 3' UTR of HMBOX1, which leads to the increased expression levels of TNF-α(transmembrane TNF-α, mTNF-α) and repressed liver cancer progression." (PMID 32201529, 2020).
Sepsis (4 papers, 2022 to 2025). Sepsis is defined as life-threatening organ dysfunction caused by a dysregulated host response to infection. "Overexpression of HMBOX1 significantly reduced the cardiomyocyte pyroptosis caused by sepsis-exos or miR-885-5p mimic." (PMID 35345489, 2022). "However, the role of miR-885-5p/HMBOX1 in sepsis and septic myocardial depression and the underlying mechanism is not fully understood." (PMID 35345489, 2022). "A recent study demonstrated that sepsis-exos increased the level of miR-885-5p, decreased HMBOX1, elevated IL-1β and IL-18, and promoted pyroptosis in AC16 cells." (PMID 39770410, 2024). "Sepsis-exos increased the level of miR-885-5p, decreased HMBOX1, elevated IL-1β and IL-18, and promoted pyroptosis in AC16 cells." (PMID 35345489, 2022). "In this study, our results indicated that overexpression of HMBOX1 inhibited the translocation of NF-κB from the cytoplasm to nuclear in sepsis-exo-treated AC16 cells." (PMID 35345489, 2022). "Sepsis-exos also decreased the expression of HMBOX1 but increased the levels of NLRP3, active caspase-1, pro-caspase-1, and GSDMD-N." (PMID 35345489, 2022). "Sepsis-exos also enhanced the secretion of IL-1β and IL-18 and decreased HMBOX1 expression in mRNA and protein levels." (PMID 35345489, 2022). "The data suggest that sepsis-exo treatment increased the pyroptosis, elevated inflammatory cytokines, but inhibited HMBOX1 in human myocardial cells." (PMID 35345489, 2022). "Sepsis-exos time-dependently elevated IL-1β and IL-18, increased miR-885-5p but decreased HMBOX1 expression." (PMID 35345489, 2022). "In short, this study revealed a new function of miR-885-5p/HMBOX1 signaling, showing that sepsis-exos-induced cardiomyocytes damage via miR-885-5p and HMBOX1." (PMID 35345489, 2022). "We showed that sepsis-exo treatment elevated IL-1β and IL-18, decreased HMBOX1, and promoted pyroptosis in AC16 cells." (PMID 35345489, 2022). "The elevated secretion of IL-1β and IL-18, and expression pattern of HMBOX1, NF-κB (cytoplasm), nuclear NF-κB, NLRP3, caspase-1, and GSDMD-N were all reversed by overexpression of HMBOX1, showing that sepsis-exos and miR-885-5p mimic had similar effects on AC16 cells." (PMID 35345489, 2022). "Sepsis-exos promoted the pyroptosis of AC16 cells through miR-885-5p via HMBOX1." (PMID 35345489, 2022). "One study found that exosomes derived from sepsis patients’ blood can upregulate miR-885-5p in AC16 cells, downregulate homeobox containing 1 (HMBOX1) and increase IL-1β and IL-18, further promoting pyroptosis of AC16 cells." (PMID 40041174, 2025). "We found that both sepsis-exos and miR-885-5p mimic promoted AC16 pyroptosis, which was abolished by overexpressing HMBOX1." (PMID 35345489, 2022). "Although many studies have been carried out, the function of miR-885-5p and HMBOX1 in cardiomyocytes and the role of sepsis in affecting myocardial function are still not fully understood." (PMID 35345489, 2022). "Moreover, levels of HMBOX1 in heart tissues were dramatically decreased, while expression of pyroptosis-related proteins NLRP3, caspase-1, and GSDMD-N were all upregulated after treatment of sepsis-exos." (PMID 35345489, 2022).
serous ovarian cancer (4 papers, 2021 to 2022). "In high‐grade serous ovarian cancer, tRF‐03357 downregulated HMBOX1, a hepatocyte nuclear factor family member." (PMID 35957621, 2022). "In high-grade serous ovarian cancer, tRF-03357 promotes cell proliferation, migration and invasion, partly by modulating HMBOX1." (PMID 34975491, 2021). "In particular in high-grade serous ovarian cancer (HGSOC), tRF-03357 may promote cell proliferation, migration, and invasion by regulating HMBOX1." (PMID 35281615, 2022). "In high-grade serous ovarian cancer, upregulated tRFs can promote protein phosphorylation, transcription, cell migration, cancer pathways, MAPK, and Wnt signaling pathways, as well as regulating HMBOX1 to attack human ovarian cancer cells." (PMID 34975491, 2021).
breast carcinoma (3 papers, 2014 to 2021). "The cis-eQTL associations of 7 genes (TAPBPL, H1F0, SERPINB9, HMBOX1, MGST3, TMBIM4, THNSL2) are shared between GBM and cell lines/normal tissues; the association of 4 genes (TAPBPL, H1F0, HMBOX1, THNSL2) are common between GBM and Breast Cancer." (PMID 25133526, 2014). "The cis-eQTL associations of H1F0, HMBOX1, and THNSL2 genes are also represented in Breast Cancer." (PMID 25133526, 2014).
glioma (3 papers, 2015 to 2024). A benign or malignant brain and spinal cord tumor that arises from glial cells (astrocytes, oligodendrocytes, ependymal cells). "At the same time, some studies have proved that miR-18a promotes the occurrence and development of glioma by regulating the expression of CBX7, HMBOX1, and ALOXE3." (PMID 38879468, 2024).
cervical cancer (2 papers, 2022 to 2025). A primary or metastatic malignant neoplasm involving the cervix. "Cervical cancer-secreted exosomal miR-1468-5p epigenetically activates the JAK2/STAT3 pathway in lymphatic endothelial cells by directly targeting homeobox containing 1 (HMBOX1) in the SOCS1 promoter, activating an immunosuppressive program that allows cancer cells to escape anti-cancer immunity." (PMID 36358833, 2022).
hepatocellular carcinoma (2 papers, 2021 to 2025). A malignant tumor that arises from hepatocytes. "As an adaptor, WTAP is overexpressed in many cancers and serves as an oncogenic protein that can down-regulate the c-Myc, HMBOX1, and ETS1 mRNAs in an m6 A-mediated manner, enhancing the proliferation and metastasis of AML, osteosarcoma, and hepatocellular carcinoma (HCC)." (PMID 40483535, 2025).
liver inflammation (2 papers, 2023 to 2024). "Furthermore, the HMBOX1/SLC1A5-mediated reduction in glutamine uptake may represent a potential mechanism underlying the protective effects of HMBOX1 in liver inflammation." (PMID 39698464, 2024). "Therefore, HMBOX1/SLC1A5-mediated downregulation of glutamine uptake may be one mechanism for the protective effects of HMBOX1 in liver inflammation." (PMID 37208615, 2023).
colon cancer (1 paper, 2021). "Therefore, we speculated that ZNF121 and HMBOX1 played a collaborative role with ZNF460 in carcinogenesis of colon cancer." (PMID 33976729, 2021).
mesenchymal neoplasms (1 paper, 2025). "This is the first case of ALK-rearranged mesenchymal neoplasm manifested as a primary lung lesion and a novel HMBOX1::ALK fusion was identified by NGS." (PMID 40463972, 2025). "The family of ALK-rearranged mesenchymal neoplasms is expanding and ensartinib could be a potential treatment option for patients with HMBOX1::ALK." (PMID 40463972, 2025).
squamous cell carcinoma of the esophagus (1 paper, 2025). "This suggests that HMBOX1 may also play a role in squamous cell carcinoma of the esophagus." (PMID 40008841, 2025).
squamous cell carcinoma of the lung (1 paper, 2025). "Homeobox containing 1 (HMBOX1), associated with telomeric DNA, exhibits high expression in squamous cell carcinoma of the lung and correlates with tumor growth." (PMID 40008841, 2025).